ZNF180 (zinc finger protein 180)
Description:
May be involved in transcriptional regulation.
Synonyms: HHZ168
Tractability: PROTAC: UniProt records ubiquitination sites on it; ubiquitination databases record sites on it.
Gene: Protein-coding gene on chromosome 19 (44,470,957 to 44,500,540, reverse strand). Ensembl gene ENSG00000167384.
Subcellular location: Nucleus
Subcellular location (Human Protein Atlas): Nucleoplasm
Pathways (Reactome):
Gene expression (Transcription): Generic Transcription Pathway
Gene Ontology:
Molecular function: protein binding; DNA-binding transcription factor activity, RNA polymerase II-specific; RNA polymerase II transcription regulatory region sequence-specific DNA binding
Biological process: regulation of transcription by RNA polymerase II; regulation of DNA-templated transcription
Cellular component: nucleus
Genetic constraint (gnomAD): Loss-of-function variants: 6 observed, 5.38 expected, observed/expected ratio (o/e) 1.12, 90% interval 0.6 to 1.85. That is too few expected variants to judge how well the gene tolerates losing a copy. Missense variants: 643 observed, 675.72 expected, observed/expected ratio (o/e) 0.95, 90% interval 0.89 to 1.02. Synonymous variants: 225 observed, 218.07 expected, observed/expected ratio (o/e) 1.03, 90% interval 0.93 to 1.15.
Homologues: Orthologues: chimpanzee ZNF180 (98% identical), macaque ZNF180 (97% identical), dog ZNF180 (85% identical), rat Zfp180 (69% identical), guinea pig ZNF180 (68% identical), mouse Zfp180 (68% identical), rabbit ZNF180 (64% identical), pig ZNF180 (53% identical). Paralogues in human: ZNF10 (35% identical), ZFP90 (31% identical), ZFP37 (31% identical), ZNF555 (27% identical), ZNF266 (26% identical), ZNF25 (25% identical), ZNF749 (25% identical), ZNF674 (25% identical), ZNF77 (25% identical), ZNF404 (25% identical), ZNF35 (24% identical), ZNF248 (24% identical), and 50 more.
Diseases named in the same sentence as ZNF180 in open-access papers:
ZNF180 is named in the same sentence as 8 diseases in open-access papers, as found by Europe PMC text mining. Sharing a sentence is not in itself a finding about the gene and the disease. The quoted sentences say what the papers report.
melanoma (3 papers, 2021 to 2024). A malignant, usually aggressive tumor composed of atypical, neoplastic melanocytes. "Experimentally validated targets of ZNF180 are enriched in the ZNF180 centered network and the known pathways such as melanoma cell maintenance and immune cell infiltration." (PMID 33619278, 2021). "This supports the role of ZNF180 in melanoma growth in vivo." (PMID 33619278, 2021). "Together, our data indicate that ZNF180 is essential for melanoma growth both in vitro and in vivo." (PMID 33619278, 2021). "It is reported that ZNF180 is involved in immune cell infiltration in melanoma cell maintenance." (PMID 34723755, 2021). "More mechanistic studies (e.g., genetic and epigenetic regulation) using immune-competent models are needed to understand the functional impact of the prioritized regulators of melanoma (e.g., MYO1F and ZNF180) on tumor progression and immune modulation." (PMID 33619278, 2021). "PAI-1 has been shown to promote macrophage infiltration in melanoma via phosphorylation of FAK-Tyr925 76, suggesting ZNF180 may also regulate immune cell infiltration in primary melanoma." (PMID 33619278, 2021).
allergic disease (1 paper, 2021). An immune response that occurs following re-exposure to an innocuous antigen, and that requires the presence of existing antibodies against that antigen. "Additionally, several proteins, whose expression could be regulated by these variants, had been previously associated with asthma-related traits and/or allergic diseases (e.g., OLFML3, PCSK3, ZNF180, GALNT16, and KLK14)." (PMID 34442380, 2021).
coronary heart disease (1 paper, 2024). "This study reveals for the first time the correlation between C5orf58, ZNF180, M1 macrophage polarization, and increased bubble cells in coronary heart disease." (PMID 39723414, 2024). "This study focuses on four biomarkers C5orf58, ZNF180, CTAG1A, and IL13RA1 that are associated with M1 macrophage polarization and bubble cell proliferation in coronary heart disease, highlighting their key roles in the pathogenesis of the disease." (PMID 39723414, 2024). "This study focuses on the roles of C5orf58, ZNF180, CTAG1A, and IL13RA1 in the polarization of M1 macrophages and the increase of bubble cells in coronary heart disease." (PMID 39723414, 2024). "According to reports, the expression of ZNF180 also showed significant differences in coronary artery disease (CAD), and the disease studied in this study belongs to the CAD type, indicating that ZNF180 plays an important role in coronary heart disease." (PMID 39723414, 2024). "At present, research on ZNF180 is relatively limited, and there have been no reports on coronary heart disease, which highlights the innovation of this study and the novelty of the results obtained." (PMID 39723414, 2024).
Fanconi anemia (1 paper, 2021). Fanconi anemia (FA) is a hereditary DNA repair disorder characterized by progressive pancytopenia with bone marrow failure, variable congenital malformations and predisposition to develop hematological or solid tumors. "On the other hand, the hubs of M22 include DNA repair regulators such as FANCM60 (a component of the Fanconi anemia core complex) and ZNF180, which has a locus associated with aberrant genomic rearrangements." (PMID 33619278, 2021).
herpes simplex infection (1 paper, 2021). "Our study identified DE TFs such as ZNF180, ZNF763, ZNF792, ZNF718, and ZNF461 associated with asthmatic ASM cells and enriched for the herpes simplex infection pathway." (PMID 34257337, 2021).
cancer (1 paper, 2021). A tumor composed of atypical neoplastic, often pleomorphic cells that invade other tissues. "Overall, our results show that ZNF180 is a multifunctional driver of oncogenic and DNA repair pathways that may also modulate tumor infiltration by M1 macrophages and cancer-associated fibroblasts." (PMID 33619278, 2021).
tumor (1 paper, 2021). "ZNF180 had the most consistent anti-tumor effects and was further validated in vivo." (PMID 33619278, 2021). "The anti-tumor effect of silencing ZNF180 is further validated using in vivo xenografts." (PMID 33619278, 2021).
ZNF180 also shares sentences with these, for which no sentence is quoted: asthma (1 paper).